CYP2E1 (cytochrome P450 family 2 subfamily E member 1)
Diseases named in the same sentence as CYP2E1 in open-access papers (continued):
Sharing a sentence is not in itself a finding about the gene and the disease.
glioma (13 papers, 2017 to 2024). A benign or malignant brain and spinal cord tumor that arises from glial cells (astrocytes, oligodendrocytes, ependymal cells). "Downregulated CYP2E1 expression, which is associated with lipid metabolism, also promotes glioma progression." (PMID 34612013, 2021). "Population studies have demonstrated a possible association between CYP2E1 polymorphisms and some brain disorders, such as PD and the risk of glioma and pain implications." (PMID 28163821, 2017). "Acetaminophen causes apoptosis and DNA fragmentation through CYP2E1 mediated JNK activation in C6 glioma cells." (PMID 28163821, 2017). "In addition, Cyp2e1 knockout significantly improved the general state of glioma‐bearing rats and counteract the tumor‐induced weight loss." (PMID 37283464, 2023). "In our study, CYP2E1 was identified as a tumor suppressor gene associated with glioma diagnosis and prognosis and could distinguish clinical molecular characteristics among glioma samples." (PMID 34612013, 2021). "DNA amplification, methylation, and hsa‐miR‐527 could be the mechanisms associated with CYP2E1 dysregulation in gliomas." (PMID 34612013, 2021). "Other mitochondrial oxidative-stress-related genes including CTSL, TXNRD2, NUDT1, STOX1, and CYP2E1 have been reported differentially expressed with potential prediction accuracy of glioma." (PMID 39012280, 2024). "This study mainly focuses on the role of CYP2E1 as a target for the prevention and treatment of glioma and CYP2E1 inhibitor in the prevention and treatment of glioma." (PMID 37283464, 2023). "The results showed no obvious pathological changes in blood biochemical indexes and organs compared with control littermates, suggesting that CYP2E1 is a safe potential target for glioma." (PMID 37283464, 2023). "Lastly, xCT expression was induced in CYP2E1-overexpressing primary mouse hepatocytes, and contributed to ferroptosis resistance in Nrf2- knockdown F98 rat glioma cells." (PMID 36993697, 2023). "Knockout of Cyp2e1 significantly attenuated brain weight and tumor weight in intracranial GBM xenograft rats, in agreement with those in Cyp2e1 knockout mice, results suggesting a prompting role of CYP2E1 in glioma." (PMID 37283464, 2023). "We also developed a potent inhibitor of CYP2E1, Q11, as an effective glioma anti‐inflammatory agent for the treatment of GBM, findings provide a perspective on anti‐inflammatory GBM therapy and offer a new potential treatment strategy for GBM." (PMID 37283464, 2023). "CYP2E1 as a new target for glioma anti‐inflammatory therapy was validated and the molecular mechanism of CYP2E1 in the tumorigenesis of glioma was further elucidated." (PMID 37283464, 2023). "In the current study, we found that CYP2E1 was remarkably higher in the glioma TME, and animal experiments further proved that CYP2E1 in TME was positively correlated with the severity of GBM." (PMID 37283464, 2023). "Six genes of these essential TrMGs, including MAOB, HSD17B10, KYNU, AOX1, and OGDH, were determined as hazardous factors for glioma patients, and other two genes (CYP2E1 and ALDH2) were identified as protective factors." (PMID 36386216, 2022). "Previous study has revealed that downregulation of CYP2E1 would promote tumor progression in gliomas, in line with our results." (PMID 36386216, 2022). "Glioma patients with low levels of CYP2E1 have a poor prognosis since the downregulation of this gene affects lipid metabolism and prevents ferroptosis in tumor tissues, leading to glioma progression." (PMID 35805884, 2022). "According to a study that demonstrated a negative correlation between CYP2E1 and immune checkpoints, changes in the expression level of CYP2E1 in glioma were related to the immunosuppressive characteristics of the tumor microenvironment." (PMID 36313348, 2022).
glioma (continued). "To further explore the mechanism by which CYP2E1 is dysregulated in gliomas, we analyzed its targeting miRNA and genetic and epigenetic alterations in TCGA glioma." (PMID 34612013, 2021). "The correlation confirmed the regulatory relationship of their expressions, the upregulation of has‐miR‐527 would lead to the downregulation of CYP2E1 mRNA in gliomas." (PMID 34612013, 2021). "Univariate and multivariate Cox proportional hazards regression, receiver operating characteristic curves, and Kaplan–Meier plots were used to evaluate the prognostic value of CYP2E1 in glioma." (PMID 34612013, 2021). "The CYP2E1 expression level was significantly lower in glioma tissues in the training set and decreased with glioma malignancy." (PMID 34612013, 2021). "Subsequently, based on the characteristics of the immune microenvironment, the effects of CYP2E1 on glioma invasion and growth were explored in this research." (PMID 34612013, 2021). "The downregulation of CYP2E1, which affects lipid metabolism and the ferroptosis signaling pathway, promotes the progression of gliomas." (PMID 34612013, 2021). "In this study, we investigated the effect of CYP2E1 on lipid metabolism and TIME to explain the underlying mechanism of the inhibition of glioma malignancy." (PMID 34612013, 2021). "Glioma samples were assigned to low and high expression groups according to the median value of CYP2E1 expression." (PMID 34612013, 2021). "No research has been conducted to investigate the carcinogenesis of CYP2E1 via ferroptosis regulation pathways in gliomas." (PMID 34612013, 2021). "In general, CYP2E1 expression was significantly downregulated in glioma tissues relative to normal brain tissues." (PMID 34612013, 2021). "Then, based on functional enrichment analysis of CYP2E1 in TCGA‐glioma, the association between CYP2E1 and tumor immune microenvironment, lipid metabolism, and ferroptosis were explored to explain these findings could translate to a novel strategy to treat glioma patient with gliomas." (PMID 34612013, 2021). "First, we identified that the downregulation of cytochrome P450 family 2 subfamily E member 1 (CYP2E1) in gliomas, CYP2E1’s expression level decreased with the degree of malignancy of gliomas." (PMID 34612013, 2021). "Functional enrichment analyses and immune infiltration analyses were performed to investigate the potential function of CYP2E1 in gliomas." (PMID 34612013, 2021). "Then, we assessed samples collected in our hospital and found that the level of CYP2E1 was significantly downregulated in glioma tissues compared with normal brain tissues and significantly decreased in GBM compared with lower‐grade glioma (LGG)." (PMID 34612013, 2021). "The Wilcoxon test was performed to analyze the correlation between CYP2E1 expression and glioma subtypes." (PMID 34612013, 2021). "K–M survival analysis of different glioma subtypes in both TCGA and CGGA cohorts indicated that downregulated expression of CYP2E1 was significantly associated with poor OS and DFS of patients." (PMID 34612013, 2021). "To further clarify whether CYP2E1 is involved in the tumorigenesis of glioma, we evaluated the relationship between CYP2E1 activity and glioma in rats." (PMID 37283464, 2023). "In addition, CYP2E1 was positively correlated with tumor size (r = 0.4204, p = 0.0185) and tumor proliferation index (r = 0.4582, p = 0.0095), indicating that CYP2E1 in TME is related to the higher malignancy of glioma." (PMID 37283464, 2023). "On the contrary, CYP2E1 was recognized as protective factor in our study, suggesting that eradication of indole, an immunosuppressive metabolites of tryptophan, would improve the prognosis of gliomas." (PMID 36386216, 2022).
glioma (continued). "CYP2E1 could be considered a novel marker of glioma, which is an important discovery related to its great significance in tumors." (PMID 34612013, 2021). "This research also shows that CYP2E1 could affect the progression and invasion of glioma cells through a variety of possible mechanisms, which confirms the great significance of research about this molecule." (PMID 34612013, 2021). "In this study, related systematic research was conducted on the role of CYP2E1 in glioma." (PMID 34612013, 2021). "Multivariate Cox logistic regression analysis in the two cohorts further confirmed that CYP2E1 expression could be an independent factor in predicting glioma patients’ prognosis." (PMID 34612013, 2021). "18beta‐glycyrrhetinic acid, styrene, toluene, nicotine, m‐xylene, p‐xylene, and colchicine may play a role in gliomas by influencing CYP2E1, which requires further study." (PMID 34612013, 2021). "CYP2E1 was predictively targeted by has‐miR‐527, which was negatively related to CYP2E1 mRNA expression (p < 0.05), which could explain the possible regulatory mechanism of CYP2E1 down‐regulation in gliomas." (PMID 34612013, 2021). "Our study found that CYP2E1 expression was significantly downregulated in gliomas and might be a potential prognostic biomarker related to the OS and DFS of patients." (PMID 34612013, 2021). "It's the first research to explore the role of CYP2E1 in gliomas." (PMID 34612013, 2021). "Glioma cells may downregulate the expression of CYP2E1 through methylation modification and DNA copy variation." (PMID 34612013, 2021). "However, the roles of CYP2E1 as a tumor suppressor or oncogene in glioma are still elusive, and its relevant regulatory mechanism and complex regulatory network still need to be fully elucidated." (PMID 34612013, 2021). "First, the characteristics of glioma samples’ clinical and molecular subtypes could be well stratified by CYP2E1 expression." (PMID 34612013, 2021). "First, CYP2E1 expression was found to correlate with the regulation of lipid metabolism in glioma." (PMID 34612013, 2021). "Systemic knockdown of Cyp2e1 in rats and mice significantly inhibited the tumorigenesis and development of glioma, with tumor inhibition rates of 61.7% and 92.0% in knockout rats and mice, respectively, suggesting that CYP2E1 may be a potential effective therapeutic target for GBM." (PMID 37283464, 2023). "The downregulation of CYP2E1 expression may predict a poor prognosis for glioma patients." (PMID 34612013, 2021). "In addition, the negative correlation between CYP2E1 and immune checkpoints also proved that downregulation of CYP2E1 expression might be related to the immunosuppressive characteristics of the microenvironment in glioma." (PMID 34612013, 2021). "To investigate the role of CYP2E1 in glioma TME, we transfected CYP2E1 plasmids into HMC3 microglia and overexpression efficiency was verified by a fluorescence signal under an inverted microscope, RT‐qPCR, and Western blotting." (PMID 37283464, 2023). "Upregulation of CYP2E1 in HMC‐3 significantly promoted proliferation and migration, and inhibited apoptosis of U251 cells, suggesting CYP2E1 is involved in tumorigenesis or progression of glioma." (PMID 37283464, 2023). "CYP2E1 expression decreased with increasing WHO grade (II–IV), and its level was correlated with clinical features, including age, 1p19q codeletion status, and IDH state in glioma tissues." (PMID 34612013, 2021). "Additionally, CYP2E1 regulates the level of ER stress and reactive oxygen species, PDIA3 is closely related to the anti‐tumour immunity of glioma, and DNM1L plays a regulatory role in the immune response of NKT cells to tumours." (PMID 33611848, 2021). "CYP2E1, identified as critical alcohol metabolizing enzyme, has not yet been systematically studied in gliomas." (PMID 34612013, 2021). "Overexpressed CYP2E1 could independently predict better OS and RFS in patients with glioma." (PMID 34612013, 2021).
gastric cancer (12 papers, 1998 to 2026). A primary or metastatic malignant neoplasm involving the stomach. "Several meta-analyses on the association between CYP2E1 polymorphisms and gastric cancers have been reported." (PMID 39063094, 2024). "Recently, a few studies on the association between the CYP2E1 polymorphism and gastric cancer have also been published, but those studies have yielded contradictory results." (PMID 22957075, 2012). "Future investigation in this area should aim to elucidate the underlying mechanisms between CYP2E1 PstI/RsaI polymorphism and gastric cancer." (PMID 22957075, 2012). "CYP2E1 PstI/RsaI polymorphism is associated with increased risk of development, progression and poor prognosis of gastric cancer in Chinese patients." (PMID 22957075, 2012). "Kaplan-Meier survival curves and log-rank test show that CYP2E1 PstI polymorphism was associated with the poor overall survival of gastric cancer." (PMID 22957075, 2012). "Characteristics of gastric cancer case-control studies included in meta-analysis on the association between CYP2E1 polymorphisms and gastric cancer." (PMID 22957075, 2012). "Our results indicating the association between the CYP2E1 polymorphism and the risk of gastric cancer are biologically plausible." (PMID 22957075, 2012). "In the meta-analysis, pooled data from 13 studies confirmed that the CYP2E1 PstI/RsaI polymorphism was associated with a significantly increased risk of gastric cancer." (PMID 22957075, 2012). "Numerous studies on the possible association of CYP2E1 RsaI/PstI polymorphisms with gastric cancer risk have been conducted." (PMID 23139769, 2012). "Our meta-analysis provided further evidence indicating an association between CYP2E1 PstI/RsaI polymorphism and gastric cancer susceptibility." (PMID 22957075, 2012). "Meta-analyses that assessed the association of CYP2E1 RsaI/PstI variations with gastric cancer were conducted." (PMID 23139769, 2012). "A case-control study was conducted in which CYP2E1 PstI/RsaI and DraI polymorphisms were analyzed in 510 Chinese patients with gastric cancer and 510 age- and sex- matched healthy controls by PCR-RFLP." (PMID 22957075, 2012). "Published studies on the relationship of CYP2E1 RsaI/PstI polymorphisms with the susceptibility to gastric cancer are controversial." (PMID 23139769, 2012). "The study also indicated that the interactions of CYP2E1 polymorphism with smoking have little association with gastric cancer risk, in contrast with the present, updated meta-analysis." (PMID 23139769, 2012). "Further investigations on the effect of the interactions of CYP2E1 polymorphism and drinking on gastric cancer are required to address this controversy." (PMID 23139769, 2012). "Further investigations with large sample sizes regarding Caucasians are needed to clarify the possible effects of CYP2E1 ethnic variations on gastric cancer risk." (PMID 23139769, 2012). "Prior to the present study, there were only two previous studies evaluating the association between CYP2E1 DraI polymorphism and gastric cancer risk." (PMID 22957075, 2012). "This coverage increased the statistical power to determine accurately the relationship between CYP2E1 RsaI/PstI polymorphisms and gastric cancer risk." (PMID 23139769, 2012). "In conclusion, CYP2E1 PstI/RsaI polymorphism is associated with development and progression of gastric cancer and poor prognosis of patients with gastric cancer." (PMID 22957075, 2012). "From the gene-environment interaction analysis, we showed effect modification of the association between SULT1A1 and gastric cancer by tobacco smoking, and CYP2E1 (*5A or *6 alleles) by alcohol drinking." (PMID 17996038, 2007). "To our knowledge, we reported for the first time a strong effect modification by alcohol of the association between CYP2E1*5A or *6 alleles and gastric cancer, with an increased risk among ever-drinkers." (PMID 17996038, 2007).
gastric cancer (continued). "However, a subgroup analysis of the smoking population showed that CYP2E1 PstI/RsaI c2 carriers demonstrated an increased risk of gastric cancers (OR, 1.56; 95% CI, 1.14–2.15) compared with c1c1 carriers." (PMID 39063094, 2024). "The abnormal expression of CYP2E1 contributes to the formation of reactive oxygen species in the gastrointestinal tract and the activation of procarcinogens such as nitrosamines, which further elevates the risk of gastric cancer." (PMID 35719924, 2022). "Association with CYP2E1 DraI polymorphism and progression of gastric cancer." (PMID 22957075, 2012). "CYP2E1 RsaI/PstI polymorphisms may modify the susceptibility to gastric cancer among individuals who have a smoking history." (PMID 23139769, 2012). "Associations between CYP2E1 polymorphisms and gastric cancer risk." (PMID 22957075, 2012). "Another interesting finding in the present study was the association of the CYP2E1 PstI/RsaI polymorphism with gastric cancer stage, which may mirror the substantial role of this polymorphism in the progression." (PMID 22957075, 2012). "It is agreed with the previous meta-analysis in 2007, which reported that CYP2E1 PstI/RsaI polymorphism may be a risk factor for gastric cancer in Asians." (PMID 22957075, 2012). "Nevertheless, the data of the present study suggested that the interactions of CYP2E1 RsaI/PstI polymorphisms with ethnic variations may exert little influence on gastric cancer susceptibility." (PMID 23139769, 2012). "Association with CYP2E1 RsaI/PstI polymorphism and progression of gastric cancer." (PMID 22957075, 2012). "In addition, we also carried out a meta-analysis of selected high quality studies published between 1990 and 2011, in order to reveal more precise association between CYP2E1 polymorphism and gastric cancer." (PMID 22957075, 2012). "Cigarette smoking can significantly accelerate chlorzoxazone metabolism and enhance the activity of CYP2E1, which may markedly activate a number of carcinogens and thereby result in increased gastric carcinoma risk among long-term smokers." (PMID 23139769, 2012). "Additionally, we showed that individuals carrying the *5A or *6 alleles of CYP2E1 are at increased risk for gastric cancer in drinkers." (PMID 17996038, 2007). "Whether CYP2E1 RsaI/PstI genetic variations can elevate the gastric cancer risk remains uncertain." (PMID 23139769, 2012). "Therefore, the aim of this study was to investigate whether CYP2E1 polymorphism is associated with the development and progression of gastric cancer and its prognosis in Chinese patients." (PMID 22957075, 2012). "Thus, the aim of the present study was to investigate whether CYP2E1 polymorphisms is associated with the development and progression of gastric cancer and its prognosis in Chinese patients." (PMID 22957075, 2012). "Thus, CYP2E1 variations may exert different influences on gastric cancer risk among different races." (PMID 23139769, 2012). "The identified synergistic interaction among GSTs null genotypes as well as the relationship between GSTM1 and CYP2E1 unfavourable variants suggest that a wide portion of gastric cancer could be attributable to the inheritance of both unfavourable polymorphisms." (PMID 19506726, 2008). "Overexpressed CYP2E1 was shown to enhance the proliferation as well as invasion of MGC-803 gastric cancer cells and inhibits their apoptosis while up-regulating the levels of intracellular p-Akt, p-mTOR and p-P70S6K." (PMID 36313348, 2022). "Mechanistic investigations showed that CYP2E1 overexpression upregulated the oncogenic PI3K-AKT-mTOR signaling pathway in gastric cancer cells." (PMID 33659048, 2021). "CYP2E1 catalyzes oxidation and DNA adduct formation of some low-molecular carcinogens of gastric cancer." (PMID 22957075, 2012). "Distribution of CYP2E1 RsaI/PstI genotype among gastric cancer cases and controls included in the meta-analysis." (PMID 23139769, 2012).